MYOCD (myocardin)
Diseases named in the same sentence as MYOCD in open-access papers (continued):
Sharing a sentence is not in itself a finding about the gene and the disease.
myocardial infarction (10 papers, 2014 to 2022). Gross necrosis of the myocardium, as a result of interruption of the blood supply to the area, as in coronary thrombosis. "Furthermore, overexpression of myocardin further improved the therapeutic potential of BM‐MSCs in a mouse model of myocardial infarction, though the underlying mechanism remains unclear." (PMID 24744906, 2014). "Myocardin, a nuclear protein was highly expressed during I/R-injury, and its downregulation repressed autophagy and diminished myocardial infarction." (PMID 34022925, 2021). "The knockdown of myocardin inhibits autophagic cell death and attenuates ischemic injury induced increase of myocardial infarction size." (PMID 29295976, 2018). "The overexpression of myocardin augmented I/R-induced myocardial infarction sizes, which was inhibited by knockdown of Beclin 1, which indicates that myocardin activates autophagy-dependent cell death in cardiomyocytes during I/R injury." (PMID 29295976, 2018). "Myocardin expression is upregulated upon H2O2 and ischemia/reperfusion, and knockdown of myocardin inhibits autophagy and attenuates myocardial infarction." (PMID 29295976, 2018). "Next, we examined the role of myocardin in the pathogenesis of myocardial infarction using experimental animal model." (PMID 29295976, 2018). "Our present study reveals that myocardin positively modulates the autophagic process in cardiomyocytes and it promotes myocardial infarction." (PMID 29295976, 2018). "Ectopic expression of myocardin further improved the therapeutic potential of BM‐MSCs in a mouse model of myocardial infarction." (PMID 24744906, 2014). "Previous studies have shown that myocardin activates cardiac gene expression in BM‐MSCs, and improved their therapeutic potential for myocardial infarction." (PMID 24744906, 2014). "It upregulates autophagy and myocardial infarction by increasing myocardin expression." (PMID 29295976, 2018). "In addition, in vivo administration of myocardin siRNA significantly reduced myocardial infarction size in the heart with I/R injury." (PMID 29295976, 2018).
myocardial infarction (continued). "However, the therapeutic effect of the ectopic expression of myocardin in iPSC‐MSCs for cardiac repair and regeneration warrants further investigation in in vivo animal models of cardiac injuries such as myocardial infarction." (PMID 24744906, 2014). "Moreover, this increase in conduction velocity might account for the superior therapeutic potential of myocardin transduced BM‐MSCs than that of BM‐MSCs themselves in the mouse model of myocardial infarction." (PMID 24744906, 2014). "We have recently shown that transplantation of AT‐MSCs overexpressing MYOCD and TERT induced an increase in the pool of cardiac resident CSCs in the infarcted cardiac tissue in a murine model of acute myocardial infarction." (PMID 33949765, 2021).
heart failure (8 papers, 2012 to 2024). Inability of the heart to pump blood at an adequate rate to meet tissue metabolic requirements. "Myocardin‐deficient adult mouse exhibits early onset of heart failure, dilated cardiomyopathy, and premature death within 1 week suggesting that myocardin is essential for the development of ventricular cardiomyocytes." (PMID 24744906, 2014). "Downregulation of MYOCD in cardiomyocytes increases apoptosis, leading to the rapid progression of dilated cardiomyopathy and heart failure." (PMID 39479514, 2024). "Collectively, these data suggested that the MYOCD inhibition can reverse the heart failure in RAL model." (PMID 30971740, 2019). "A close examination of the findings identifies the MYOCD-related transcriptional cofactors as putative therapeutic targets to improve cardiac function in heart failure conditions through distinct context-dependent mechanisms." (PMID 22666593, 2012). "This suggests that the sustained high concentration of MBNL1 may contribute to heart failure via Myocardin and TNF‐α." (PMID 33295096, 2021). "Another paper in this issue, by A. T. Mikhailov and M. Torrado, focuses on the role of myocardin and myocardin-related transcription factors (MRTF) in heart failure and cardiac hypertrophy." (PMID 23304510, 2012).
aneurysm (5 papers, 2015 to 2025). Bulging or ballooning in an area of an artery secondary to arterial wall weakening. "In aneurysmal AngII‐treated mice, overall media myocardin level, α‐SMA level, and cell count were also decreased, which indicates substantial loss of VSMC in the cell media specifically in response to aneurysm formation." (PMID 36117398, 2022). "Each of these genes is regulated directly by myocardin in the postnatal vasculature confirming that dysregulated myocardin-dependent transcription can be directly involved in aneurysm formation in humans." (PMID 28790933, 2017). "Moreover, while KO of MYOCD in SMCs results in aortic aneurysms with dissection and rupture, aneurysm propensity in SRF-deficient mice has not been examined." (PMID 40081573, 2025).
lung carcinoma (5 papers, 2020 to 2023). "We further analyzed TCGA data and found that the expression of MYOCD was positively associated with overall survival of lung cancer patients (left)." (PMID 33995678, 2021). "Of note, we revealed that around 32% of Kras mutation positive lung cancer patients concurrently had low expression of MYOCD (designated K+/M- patients)." (PMID 33995678, 2021). "Our current work shows that loss of function of MYOCD creates Achilles' heels in lung cancer cells, which might be exploited in clinic." (PMID 33995678, 2021). "Importantly, TGFBR kinase inhibitor and cancer stemness inhibitor synergize with existing drugs to treat lung cancer deficient of MYOCD." (PMID 33995678, 2021). "Taken together, our results suggested that TGFBR inhibitors and CSC stemness inhibitors may synergize with current drug for treating MYOCD-deficient lung cancers." (PMID 33995678, 2021). "We have shown that TGFBR inhibitors exhibited exquisite cytotoxicity to NSCLC cells with loss of function of MYOCD, which could be exploited in lung cancer therapy." (PMID 33995678, 2021). "We then checked whether inhibitors against stemness or TGFBR could synergize with current therapeutics for treating MYOCD-deficient lung cancers." (PMID 33995678, 2021). "TGFBRi and stemness inhibitor synergize with existing drugs to treat MYOCD deficient lung cancers." (PMID 33995678, 2021). "Lastly, MYOCD which is an essential tumor suppressor gene in specific lung cancers was predicted to have a significantly down regulated activity." (PMID 37843125, 2023). "To further investigate its TSG function in vivo, we overexpressed MYOCD in pulmonary epithelia of lung cancer transgenic mice." (PMID 33995678, 2021). "To further investigate the function of MYOCD in lung cancer, we set out to generate lung cancer cell lines for inducible overexpression or knockdown of MYOCD." (PMID 33995678, 2021). "Of note, we also saw the same trend in stage I lung patients (right), strongly suggesting that MYOCD was a clinically relevant TSG in lung cancer." (PMID 33995678, 2021). "To model clinical settings of MYOCD deletion in lung cancer, we tested the impact of MYOCD knockout on lung cancer development using lsl-KrasG12D transgenic mice, a model widely accepted to faithfully recapitulate the clinical course of lung cancer patients." (PMID 33995678, 2021). "CT imaging revealed that deletion of MYOCD significantly promoted KrasG12D-driven lung cancer progression." (PMID 33995678, 2021). "CRISPR/CAS9 mediated deletion of MYOCD significantly promoted the growth and development of lung cancer in mouse model of autochthonous NSCLC while lentivirus mediated overexpression significantly inhibited lung cancer development." (PMID 33995678, 2021). "We went on to test the ability of MYOCD to inhibit stemness of lung cancer on SCID mice through in vivo limiting dilution assay, a widely accepted method to determine the frequency of tumor initiating cell of an established cell line." (PMID 33995678, 2021). "For this purpose, we generated a cohort of KrasG12D/MYOCD-/- (K-sgMYOCD) transgenic mice and randomized them for treatments with above combinational scheme after lung cancers were documented by CT scanning." (PMID 33995678, 2021). "In vitro studies reveal potent suppressive role of MYOCD in colony formation of lung cancer cell lines in 2-D and soft-agar culture conditions." (PMID 33995678, 2021). "Taken together, these results consistently showed that MYOCD is an inhibitor of stemness of lung cancer cells." (PMID 33995678, 2021). "Taken together, our data showed that MYOCD inhibited lung cancer cell stemness through inhibiting TGFBR2 transcription." (PMID 33995678, 2021). "Our previous in-vivo screening suggested that somatic knockout (KO) of MYOCD tended to promote tumor progression of KrasG12D driven lung cancer." (PMID 33995678, 2021).
lung carcinoma (continued). "However, our analysis of TCGA data has also shown that inactivation of MYOCD is an early event in development of lung cancer." (PMID 33995678, 2021). "Of note, we found that MYOCD mRNA level in clinical samples was almost universally low as reflected by Fragments Per Kilobase of transcript per Million (FPKM) in RNA-sequencing data of 994 lung cancer samples analyzed (FPKM<1 in 98% patients)." (PMID 33995678, 2021). "Consistently, we found significantly lower expression of MYOCD mRNA levels in lung cancer samples." (PMID 33995678, 2021). "We find that MYOCD negatively regulates stemness of lung cancer cells." (PMID 33995678, 2021). "Further analysis reveals that MYOCD potently inhibits stemness of lung cancer stem cells." (PMID 33995678, 2021). "Experimental Design: MYOCD is a clinically relevant TSG in lung cancer patients." (PMID 33995678, 2021). "MYOCD, RSPO1 and ARHGAP20 have all been implicated in various cancers, including lung cancer." (PMID 32899298, 2020). "We then wonder whether MYOCD functions as an inhibitor of stemness of lung cancer cells." (PMID 33995678, 2021). "Collectively, our data solidly showed that MYOCD recruited PRMT5/MEP50 methyltransferase complex and epigenetically modified TGFBR2 promoter region to silence its transcription in lung cancer cells." (PMID 33995678, 2021). "Collectively, our data suggested that MYOCD was a potent and clinically relevant TSG in lung cancer." (PMID 33995678, 2021). "Our above data suggested that MYOCD inactivation led to TGFBR2 hyperactivation and enhanced stemness of lung cancer cell." (PMID 33995678, 2021). "Of note, knockdown of MYOCD didn't significantly promote the A549 cell to grow colonies in 2-D plate, suggesting that 2-D colony formation ability may not be a consistent phenotype on lung cancer cells elicited by MYOCD knockdown." (PMID 33995678, 2021).
diabetes (4 papers, 2018 to 2024). "Perturbations in MYOCD, are associated with heart failure, acute vessel disease, diabetes and cancer, with some MYOCD-related transcription factors regulating cytoskeletal dynamics which can benefit tumour migration and invasion." (PMID 37146029, 2023). "In this study, we found that Rosiglitazone treatment restored myocardin expression in Atp6v0d1AKO mice, suggesting that myocardin downregulation is a result of the systemic insulin resistance that occurs in diabetes, obesity and lipodystrophy." (PMID 38505620, 2024).
dilated cardiomyopathy (4 papers, 2014 to 2024). Cardiomyopathy which is characterized by dilation and contractile dysfunction of the left and right ventricles. "The MBM‐containing isoform of MYOCD is expressed also in human cardiovascular tissues, and its expression level is increased in the failing hearts of patients with dilated cardiomyopathy." (PMID 36610028, 2023).
Hypertension (4 papers, 2017 to 2025). The presence of chronic increased pressure in the systemic arterial system. "ROCK is a novel mediator modulating aortic VSMC stiffness through SRF/myocardin signaling which offers a therapeutic target to reduce aortic stiffening in hypertension." (PMID 29169155, 2017). "We here hypothesized that Rho kinase (ROCK) acts as a novel mediator that regulates intrinsic VSMC mechanical properties through the serum response factor (SRF)/myocardin pathway and consequently regulates aortic stiffness and blood pressure in hypertension." (PMID 29169155, 2017). "S-nitrosylation of the transcription cofactor myocardin attenuates the phenotypic marker expression of VSMC contractility and vasoconstriction in systemic hypertension." (PMID 40867518, 2025). "In addition, our most recent study demonstrated that serum response factor (SRF)/myocardin pathway acts as a pivotal mediator of aortic VSMC stiffening and plays a central role in the pathological aortic stiffening in hypertension." (PMID 29169155, 2017). "Selective inhibition downstream of ROCK signaling, e.g., by targeting SRF/myocardin as with CCG-100602, provides a new avenue to the development of safer therapies by specifically targeting the pathological alterations of hypertension while minimizing off-target effects." (PMID 29169155, 2017).
leiomyosarcoma (4 papers, 2012 to 2023). An uncommon, aggressive malignant smooth muscle neoplasm, usually occurring in post-menopausal women. "In human uterine leiomyosarcoma cells, myocardin in conjunction with SRF directly binds to the p21 promoter and induces its expression, thus resulting in G1/S arrest." (PMID 25888165, 2015). "We also identified a focal amplification on 17p that specifically covered most of the MYOCD gene locus that was recently shown to be frequently amplified and over-expressed in at least one subset of leiomyosarcomas." (PMID 23209738, 2012). "By integrating large-scale data, we identified two specifically deregulated pathways involved in differentiation/proliferation switch (MYOCD/SRF and E2F1/RB1) in a subgroup of well-differentiated vascular smooth muscle cell-derived cells leiomyosarcomas." (PMID 36672483, 2023). "Myocardin impairs the proliferation of vascular smooth muscle cells, Chinese hamster ovarian (CHO) cells, and leiomyosarcoma cells." (PMID 25888165, 2015).
coronary artery disease (3 papers, 2023 to 2025). "Moreover, SRF-myocardin axis has been shown to be antagonized by the over-expression of the coronary artery disease-risk gene Tcf21 in vivo." (PMID 41246212, 2025). "Transcription factor 21 (TCF21), a basic-helix-loop-helix transcription factor that contributes to the risk of coronary heart disease, blocks the MYOCD-SRF pathway via direct TCF21-MYOCD interaction and results in a less differentiated phenotype." (PMID 36604627, 2023).
myocardial ischemia (3 papers, 2018 to 2024). A disorder of cardiac function caused by insufficient blood flow to the muscle tissue of the heart. "Overexpression of MYOCD enhances the protective effect of MSCs against myocardial ischemia injury." (PMID 39479514, 2024).
non-small cell lung carcinoma (3 papers, 2022 to 2023). A group of at least three distinct histological types of lung cancer, including non-small cell squamous cell carcinoma, adenocarcinoma, and large cell carcinoma. "MYOCD acts as a tumor suppressor by inhibiting stemness in non-small cell lung carcinoma (NSCLC), downregulated in lung squamous cell carcinoma and lung adenocarcinoma." (PMID 38110859, 2023).
sarcoma (3 papers, 2020 to 2024). A usually aggressive malignant neoplasm of the soft tissue or bone. "Additionally, MYOCD amplification, PTEN deletion/mutation, and activation of AKT/mTOR pathways were enriched compared to other sarcoma subtypes." (PMID 38473300, 2024). "Similarly, fusions involving driver genes largely or exclusively restricted to sarcoma (e.g. KMT2A::YAP1 in case 9) are readily detectable, as are the more sarcoma-specific copy number targets (e.g. COPS3 in case 17 and MYOCD in case 13)." (PMID 38997407, 2024).
Alzheimer disease (2 papers, 2021 to 2025). A progressive, neurodegenerative disease characterized by loss of function and death of nerve cells in several areas of the brain leading to loss of cognitive function such as memory and language. "For instance, transcription factors such as SRF and MYOCD are highly expressed in Alzheimer’s disease." (PMID 40166460, 2025). "In Alzheimer's disease, overexpression of SRF and myocardin in small cerebral arteries was shown to contribute to the pathogenesis of the condition as they increase arterial contractility and reduced blood flow due to the activation of SRF‐dependent SM contractile genes." (PMID 32885587, 2021).
aortic aneurysm (2 papers, 2025). A ruptured aneurysm located in the wall of the proximal portion of the descending aorta proceeding from the arch of the aorta. "Although the underlying mechanisms remain unclear, recent research indicates the pivotal role of the XBP1u‐FoxO4‐myocardin axis in maintaining the VSMC contractile phenotype and preventing phenotypic switching during aortic aneurysm formation." (PMID 41497804, 2025).